INS (insulin)
Diseases named in the same sentence as INS in open-access papers (continued):
Sharing a sentence is not in itself a finding about the gene and the disease.
diabetes (continued). "At baseline, gender distribution, mean age, ethnicity, duration of diabetes and HbA1c were similar in the two groups, although the mean body weight, BMI and TDD of insulin were higher in the tirzepatide group than in the control group." (PMID 40004833, 2025). "Her medical history included type 2 diabetes mellitus (T2DM), which was managed with insulin, and a history of obstetric cholestasis, for which she was treated with ursodeoxycholic acid from 20 weeks of gestation." (PMID 40416257, 2025). "Anti-insulin mouse BCR (mAb 125) expressed as human IgG1 (humAb 125) was designed as a positive control, as the murine version of this mAb supports diabetes development in NOD mice." (PMID 41259806, 2025). "Stringent glycemic control and/or using insulin either as a replacement for or in addition to oral hypoglycemic agents (OHAs) has been recommended for people with tuberculosis and diabetes mellitus (TB-DM)." (PMID 40680017, 2025). "In rodent models of diabetes, administration of exogenous PYY3–36 has resulted in greater glucose-stimulated insulin secretion and suppression of excess glucagon release." (PMID 41228539, 2025). "Evaluation is performed using datasets, such as PIMA Indian, Frankfurt Hospitals Diabetes, RTML with Insulin, and the proposed Diabetes Health Tracer (DHT) dataset comprising 2877 observations with nine features." (PMID 41118429, 2025). "However, it is important to note that this continuous effect of CGM on glycemic outcomes might only be achievable by using CGM-specific insulin titration algorithms and diabetes-educated staff (eg, in-hospital diabetes teams) to actively act on CGM data, avoiding clinical inertia." (PMID 40980547, 2025). "Eight studies reported at least one of the following glucose metabolism parameters: FPG, f-INS, HOMA-IR, HOMA%S, HbA1c, 2h-OGTT or prevalence of diabetes." (PMID 40259008, 2025). "With the development of more stable insulin analogues and FRC, we have more options for personalized treatment of diabetes mellitus." (PMID 41268167, 2025). "In the context of chronic kidney disease and diabetes, available data comparing SGLT2 inhibitors with standard care, sulphonylureas, DPP-4 inhibitors, or insulin remain inconclusive and are characterized by a degree of uncertainty." (PMID 40574081, 2025). "The patient developed diabetes mellitus (DM) postoperatively which was managed with insulin." (PMID 40714667, 2025). "Rodent studies reveal that phthalates exacerbate diabetes by activating PPARγ, impairing GLUT-2, and disrupting insulin signalling, often with sex-dependent differences." (PMID 41488239, 2025). "Comparing basal insulin prescription patterns, fCGM users were prescribed ultralong-acting analogs more frequently than those who perform BGM for all types of diabetes." (PMID 39901274, 2025). "Insulin secretion is impaired in individuals with IGT and type 2 diabetes, and the prevalence of both IGT and diabetes was higher in the older groups." (PMID 40002793, 2025). "Collectively, impaired insulin signaling and dysregulated glucose metabolism by constitutive induction of Nrf1-Tg:MGRD results in the development of diabetes mellitus triggered by the high fat diet." (PMID 40703332, 2025). "DPP-IV is an enzyme that degrades GLP-1, a crucial incretin hormone involved in insulin secretion and glucose regulation, positioning DPP-IV inhibition as a key therapeutic target for diabetes." (PMID 40509480, 2025). "In rats with diabetes induced by feeding an HFD and treated with STZ, blood insulin levels were reduced, while quercetin treatment restored concentrations of insulin to normal values." (PMID 40806520, 2025). "Diabetes mellitus (DM) is a metabolic disease characterized by hyperglycemia (elevated blood glucose), which is caused by a lack of insulin or failure of insulin, resulting in cells being unable to absorb glucose, thus increasing blood glucose levels." (PMID 40520185, 2025).
diabetes (continued). "New technologies like continuous glucose monitors (CGMs) and automatic insulin delivery systems (AID, sometimes known as the artificial pancreas) have revolutionised diabetes management." (PMID 40520684, 2025). "Currently, type 2 diabetes mellitus (DM) is a chronic metabolic disorder that results either from insufficient insulin production and secretion by the pancreas or a combination of insulin resistance in peripheral tissues and inadequate insulin production to compensate for this resistance." (PMID 40509318, 2025). "Insulin icodec is a novel once-weekly basal insulin analog subcutaneous injection seeking approval by the United States Food and Drug Administration (FDA) for use in both type 1 and type 2 diabetes mellitus." (PMID 40156735, 2025). "Type 2 diabetes mellitus (T2DM) arises from insulin resistance, characterized by reduced target organ sensitivity to insulin, coupled with insufficient pancreatic beta-cell insulin secretory capacity, collectively leading to hyperglycemia." (PMID 41586316, 2025). "Although 26.9 million individuals in America have type 1 diabetes mellitus (T1DM) or type 2 diabetes mellitus (T2DM), exercising is more difficult for those dependent upon insulin, which includes all persons with T1DM." (PMID 40271321, 2025). "The results obtained in this study were as follows: IGF-1, History of Diabetes Mellitus, HbA1c, Insulin, Education Years, SBP, C-Peptide, DBP, Age, Total Cholesterol, Anti-Insulin Antibody, FBG, LDL-C, Triglyceride, White Matter Lesion (WML), and Sex." (PMID 39963470, 2025). "This method helps to moderate the amount of intake based on individual differences in metabolic demands, increases insulin sensitivity, and may have helpful effects on long‐term consequences, such as decreasing the chances of renal failure and cardiovascular diseases commonly related to diabetes." (PMID 41030838, 2025). "For diabetes management, NIR-responsive black phosphorus microneedles deliver insulin in a glucose-sensitive manner, minimizing frequent injections." (PMID 40136911, 2025). "Diabetes medications in the OB+/DM+ group included biguanides (78.6%), secretagogues, SGLT2 inhibitors and insulin (7.1% of each)." (PMID 41561152, 2025). "In the context of diabetes, particular interest has been directed toward probiotics engineered to secrete GLP-1, aiming to stimulate insulin secretion and improve glycemic control." (PMID 41584842, 2025). "The KDIGO guideline for the management of diabetes and CKD comment that with elevated HbA1c, insulin, or GLP-1 receptor antagonist can be started." (PMID 40352967, 2025). "Obeticholic acid (OCA), a semisynthetic derivative of the natural bile acid chenodeoxycholic acid, can improve insulin sensitivity and reduce biomarkers of liver fibrosis in NAFLD patients with type 2 diabetes mellitus." (PMID 40142198, 2025). "Enteric-coated oral insulin capsules (ORMD-0801) have been used to treat both type-1 and type-2 diabetes mellitus." (PMID 39815320, 2025). "In patients with diabetes, FMD consistently improved glucose metabolism, insulin sensitivity, and long-term glycemic control, with notable reductions in HbA1c and fasting glucose." (PMID 40137116, 2025). "Recent advances in diabetes management feature dual incretin receptor agonists, like tirzepatide, which combine GLP-1 and GIP receptor agonism, resulting in increased insulin secretion, decreased glucagon release, and significant weight loss." (PMID 40395625, 2025). "Patients with type 1 diabetes mellitus, ketosis, DKA or acute complications were excluded, and insulin therapy was initiated on day 0, the day before SGLT2 inhibitor administration." (PMID 40828947, 2025). "In short-term RCTs lasting an average of a few months, vitamin D supplementation has reduced fasting plasma glucose and insulin concentrations among participants without diabetes, but the benefits may be restricted to high-risk populations, that is, those with impaired glucose metabolism." (PMID 39621103, 2025).
diabetes (continued). "Insulin therapy was more commonly observed in the ISR group, suggesting a link between advanced diabetes and poor vascular outcomes." (PMID 40978996, 2025). "Thus, the skin-permeable polymer may enable non-invasive transdermal delivery of insulin, relieving patients with diabetes from subcutaneous injections and potentially facilitating patient-friendly use of other protein- and peptide-based therapeutics through transdermal delivery." (PMID 41261125, 2025). "Then, after adding diabetes duration, SBP, TG, HDL-C, and LDL-C (Model 2) or diabetes duration, SBP, TG, HDL-C, LDL-C, smoking status, use of insulin therapy, and HbA1c (Model 3) as a confounding factor, the TIR was still an independent risk factor for CAD." (PMID 40486927, 2025). "Our analytic approach, which used both ridge regression to reduce multicollinearity and subgroup phenotyping, diverges from traditional models and may explain why non-insulin-treated diabetes emerged with a stronger association than insulin-treated or obese phenotypes." (PMID 41153651, 2025). "Compared to insulin naïve and BOT patients, MDI patients were more frequently men, were older, with longer diabetes duration and higher BMI." (PMID 39235480, 2025). "Type 1 diabetes mellitus (T1DM) is a chronic autoimmune condition, characterized by the destruction of the insulin-producing pancreatic beta cells, tasked with insulin production." (PMID 41257445, 2025). "Type 2 diabetes mellitus (T2DM), which results from inadequate insulin production or insulin resistance, accounts for approximately 90% of diabetes cases in the adult population." (PMID 40724270, 2025). "In diabetes, chronic ER stress and sustained UPR activation impair insulin signaling in the liver and adipose tissue, worsen hepatic steatosis, and compromise pancreatic β-cell function, which are the core mechanisms of insulin resistance and T2DM." (PMID 41465308, 2025). "Type 1 diabetes mellitus (T1DM) is a chronic autoimmune disorder where the immune system targets and destroys insulin‐producing β‐cells in the pancreas." (PMID 40765373, 2025). "Future studies should clarify the relationship between diabetes and sarcopenia in MASH-related cirrhosis by incorporating these factors, including therapeutic strategies and insulin dynamics." (PMID 41464593, 2025). "DPP-4Is are approved for the treatment of type 2 diabetes mellitus; they provide glycemic control by increasing GLP-1 levels and insulin release and reducing glucagon secretion and hepatic glucose output." (PMID 40048376, 2025). "Ninety‐eight percent of children with diabetes mellitus are T1DM, which requires lifelong therapeutic management with glucose monitoring, insulin injection, diet, exercise and health education." (PMID 40256125, 2025). "Type 2 diabetes mellitus (T2DM) is a chronic metabolic disorder characterized by insulin resistance and impaired insulin secretion." (PMID 41337811, 2025). "Therefore, we evaluated whether use of CGM in combination with five classes of anti‐diabetes medications was associated with changes in A1c among people with type 2 diabetes not using insulin." (PMID 40851538, 2025). "Within the field of diabetes research, BDNF is considered a crucial element in enhancing glucose metabolism and insulin sensitivity, serving as an essential mediator in the pathophysiological mechanisms underlying T2DM." (PMID 40933306, 2025). "Participants with diabetes were finally diagnosed with T1DM if they had a prior diagnosis of T1DM at the onset and continuously received basal-bolus insulin treatment during two years." (PMID 41225468, 2025). "In Alström syndrome, diabetes is common due to ALMS1 gene-related defects in ß-cell function and peripheral insulin signaling." (PMID 41480351, 2025). "The availability of advanced diabetes technologies such as continuous glucose monitoring (CGM), automated insulin delivery (AID) and the use of insulin analogues have been shown to improve glycemic control and reduce hypoglycemia." (PMID 40512259, 2025).
diabetes (continued). "A relative deficiency of insulin or a lack of sensitivity to endogenous insulin reduces glucose tolerance and can cause diabetes mellitus (DM)." (PMID 40136391, 2025). "Although the mechanism is not clearly understood, the asynchronous insulin response in GRH indicates a sign of glucose dysmetabolism, as akin to some form of impaired glucose tolerance or diabetes during pregnancy." (PMID 40859194, 2025). "Given their pivotal role in diabetes management, it is essential to assess family medicine residents (FMRs)' knowledge, attitudes, and practices (KAP) regarding insulin titration to ensure optimal patient outcomes." (PMID 40909026, 2025). "Advances in diabetes care, including continuous glucose monitoring (CGM), insulin pumps (IP), and, more recently, smart multiple-dose injection (MDI) pens, have substantially improved glycaemic control and quality of life in paediatric patients." (PMID 41003281, 2025). "The most common type of diabetes is type 2 diabetes mellitus (T2DM), which is characterised by insufficient insulin secretion or insulin receptor desensitisation, which prevents glucose from entering the cells." (PMID 41210054, 2025). "Type 1 diabetes mellitus (T1DM) requires lifelong management, yet access to insulin, specialized care, and education is limited in low- and middle-income countries (LMICs)." (PMID 41040711, 2025). "This can impact the quality and effectiveness of multidisciplinary team support offered and received and the diabetes technologies offered or made available to CYPD (eg, the latest insulin pumps and continuous glucose monitoring devices)." (PMID 40335137, 2025). "Type 1 diabetes mellitus (T1DM) is a chronic autoimmune disorder marked by T-cell-mediated destruction of pancreatic β-cells, leading to impaired insulin secretion in the pancreatic islets of Langerhans." (PMID 40507468, 2025). "Previous studies have shown that Tirzepatide can improve insulin sensitivity and maintain glucose homeostasis by activating GLP-1 and GIP receptors, thereby indirectly alleviating diabetes-induced hyperglycemia and subsequent renal injury." (PMID 41458627, 2025). "Based on differences in pathogenesis, DM is mainly classified into type 1 diabetes mellitus (T1DM) and type 2 diabetes mellitus (T2DM), of which T1DM is insulin-dependent." (PMID 40959086, 2025). "For diabetes medication, which indicated whether a patient was on insulin, non-insulin medications, or neither, encoding values ranged from 0 for no medication, 1 for non-insulin medications, and 2 for insulin." (PMID 41156040, 2025). "The high blood glucose and low fed insulin levels indicated a diabetes model had been set up, and simultaneously STZ eliminated the difference in serum insulin levels (after meal) between the WT and LKO mice (Fig. EV6B,C)." (PMID 40760121, 2025). "In diabetes, vanillic acid shows favorable properties by activating the AMPK/Sirt1/PGC-1α pathway, modulating insulin signaling pathways such as Akt and ERK1/2, and regulating enzymes and proteins involved in glucose and lipid metabolism." (PMID 39850111, 2025). "Type 2 Diabetes Mellitus (T2DM) is a complex endocrine and metabolic disorder characterized by chronic hyperglycemia and impaired insulin sensitivity." (PMID 41306436, 2025). "Inadequate glycaemic control was higher in those with diabetes for ≥10 years (74%) versus those with a shorter duration (63%) and in participants treated with both OAD and insulin (81%) compared with those treated with a single OAD (59%)." (PMID 41395632, 2025). "A larger study of the entire Project ECHO Diabetes' stepped wedge trial demonstrated a statistically significant increase in both CGM use and insulin pump use among adults with T1D and T2D using MDI at all participating FQHCs." (PMID 40678170, 2025). "The pathological feature of GDM, like type 2 diabetes mellitus (T2DM), is correlated with both defective insulin secretion and insulin resistance." (PMID 41488874, 2025).
diabetes (continued). "Participants using intensive insulin therapy reported significantly higher (p < .0001) TBQ + D scores (61.4, SD 41.9) than patients receiving other diabetes treatments (37.8, SD 36.3)." (PMID 40894032, 2025). "In accord, the coupling between glucose stimulus and insulin secretion is also disrupted in type 2 diabetes mellitus (T2DM), with increased insulin secretory output allowing for temporary normalisation of glycaemia." (PMID 39255356, 2025). "This difference persisted in sensitivity analyses of patients with uncontrolled diabetes (AOR, 0.59; 95% CI, 0.46-0.75; P < .001) and patients using insulin (AOR, 0.70; 95% CI, 0.60-0.81; P < .001)." (PMID 40526387, 2025). "In the context of the islet β-cell, significant defects in the exocytotic proteins involved in insulin secretion (e.g., SNARE proteins) have been reported in diabetes." (PMID 40598917, 2025). "Type 2 diabetes (T2DM), the most common, affecting > 90% of people diagnosed with DM, results from an inability of pancreatic β-cells to produce adequate insulin to stimulate glucose utilization by peripheral metabolically active organs to maintain glucose homeostasis." (PMID 39883142, 2025). "As an endogenous inhibitor of glucose-stimulated insulin secretion (GSIS), PGE2 plays an important role in type 2 diabetes mellitus (T2DM)." (PMID 40028769, 2025). "Type 1 diabetes mellitus (T1DM) constitutes 2%–5% of diabetes, and the disease is steadily rising worldwide; insulin replacement is the mature cornerstone therapeutic option." (PMID 40852189, 2025). "Compared with other non-insulin-dependent surrogate indices such as TyG, METS-IR has shown superior predictive value for visceral obesity, incident diabetes, and metabolic disorders." (PMID 41180178, 2025). "Moreover, a recent study examining affordability of essential medicines found that 51.4% of Indian households with diabetes members were unable to afford insulin and 24.6% couldn’t afford metformin, with the highest unaffordability reported in rural areas and among the lowest income tertile." (PMID 40358737, 2025). "Type 2 diabetes mellitus (T2DM) refers to a chronic metabolic disorder that results from insulin resistance, leading to impaired insulin action and uncontrolled plasma glucose levels." (PMID 41280372, 2025). "To date, there is a gap in research comparing the cost-effectiveness and quality of life between new insulin therapies and the insulin-free lifestyle afforded by SPKT for patients with diabetes and renal failure." (PMID 41536839, 2025). "Over the last few decades, a stepwise change in diabetes management has been the introduction and widespread uptake of novel technologies, including continuous glucose monitoring (CGM) and automated insulin delivery (AID) systems." (PMID 40520684, 2025). "He had been diagnosed with type 1 diabetes mellitus (T1DM) in his home country 2 months earlier and had initiated insulin therapy at that time." (PMID 40381102, 2025). "Similarly, the mortality risk was higher among patients with diabetes than in those without the condition, suggesting that impaired blood glucose metabolism or insulin resistance may exacerbate the inflammatory response." (PMID 40211815, 2025). "This real-world study included patients with type 2 diabetes mellitus (T2DM), who were poorly glycemic controlled on premixed insulin therapy and were subsequently added vildagliptin." (PMID 40620795, 2025). "It is important to note that insulin remains the cornerstone therapy for hyperglycemic ICU patients, including those with undiagnosed diabetes mellitus, as it is effective in relieving acute hyperglycemia and ketoacidosis." (PMID 40469441, 2025). "Low ADPN levels are correlated with obesity, hypertension, and diabetes, whereas elevated ADPN levels enhance glucose uptake and FAO via AMPK activation, improving insulin sensitivity." (PMID 41345744, 2025).